TREM2 (triggering receptor expressed on myeloid cells 2)
Diseases named in the same sentence as TREM2 in open-access papers (continued):
Sharing a sentence is not in itself a finding about the gene and the disease.
amyotrophic lateral sclerosis (55 papers, 2014 to 2025). Amyotrophic lateral sclerosis (ALS) is a neurodegenerative disease characterized by progressive muscular paralysis reflecting degeneration of motor neurons in the primary motor cortex, corticospinal tracts, brainstem and spinal cord. "TREM2 coding variants have also been associated with increased risk for amyotrophic lateral sclerosis (ALS) and frontotemporal-lobar dementia (FTLD)." (PMID 29037207, 2017). "TREM2 mutations have also been identified as risk factors for Parkinson's disease (PD), amyotrophic lateral sclerosis (ALS), and FTD." (PMID 28149270, 2016). "Interestingly, targeting the TREM2-APOE pathway can restore the homeostatic phenotype of microglia in amyotrophic lateral sclerosis (ALS) and AD mice models, and prevented neuronal loss in an acute neurodegeneration model." (PMID 37818457, 2023). "DAM subpopulation-involved pathology is apparent in AD models and is also reported in TREM2-APOE pathway models of amyotrophic lateral sclerosis (ALS) and multiple sclerosis (MS)." (PMID 36902168, 2023). "Additionally, studies have shown that TREM2 expression is upregulated upon inflammatory insult and/or neurodegenerative disease, including Parkinson’s disease (PD), amyotrophic lateral sclerosis (ALS), stroke, traumatic brain injury, and AD." (PMID 40400621, 2025). "DAM, which depend on the triggering receptor expressed on myeloid cells 2 (TREM2), are observed in aging, AD, frontotemporal dementia, and amyotrophic lateral sclerosis (ALS)." (PMID 39062547, 2024). "Mutations and polymorphisms of the TREM2 gene are associated with a significant increase in the risk of AD, but it will not increase the risk of Amyotrophic Lateral Sclerosis (ALS) and PD." (PMID 38020891, 2023). "TREM2 expression is up regulated in pathological conditions such as Parkinson’s disease (PD), Amyotrophic lateral sclerosis (ALS), stroke, traumatic brain injury and AD." (PMID 30572908, 2018). "There is increasing evidence that TREM2 regulates microglia-mediated neuroinflammation and thus play an important role in neurodegenerative diseases, such as AD, PD and amyotrophic lateral sclerosis (ALS)." (PMID 35003116, 2021). "It was shown that microglia uniformly downregulate their homeostatic signature genes, such as Sall1, Pu.1, Tmem119, Cx3cr1, and P2ry12/13 and upregulate risk genes for AD, such as Apoe and Trem2, in mouse models for aging, AD (5XFAD and APP-PS1), and amyotrophic lateral sclerosis (ALS) (SOD1)." (PMID 30108586, 2018). "Similarly, in the model of amyotrophic lateral sclerosis (ALS) - mSOD1, microglia showed a reduction of the core microglial genes Tmem119 and P2ry12 and upregulated Trem2, Tyrobp, Lpl, and Cst." (PMID 33809675, 2021). "A subsequent study further confirmed that the activation of TREM2-APOE signaling pathways in DAM is essential for the switch of homeostatic microglia to DAMs during the pathogenesis of various neurodegenerative diseases including AD, amyotrophic lateral sclerosis (ALS) and multiple sclerosis (MS)." (PMID 35693341, 2022). "Studies showed that expression of TREM2 is upregulated in a wide range of diseases, namely AD, PD, TBI, stroke, and amyotrophic lateral sclerosis (ALS)." (PMID 35401152, 2022). "The rs75932628 variant of the TREM2 gene was also not identified in a Chinese population with PD, multiple system atrophy (MSA), and amyotrophic lateral sclerosis (ALS)." (PMID 32842621, 2020).
cognitive decline (53 papers, 2016 to 2026). "Elevated concentration of CSF soluble TREM2 (sTREM2), cleaved from the membranes of microglia or monocytes, is linked to disease progress cognitive decline in AD and FTLD." (PMID 39472664, 2025). "The increase in the soluble extracellular segment of TREM2 (sTREM2) in cerebrospinal fluid of PD patients seems to be associated with increased risk of cognitive decline." (PMID 40309835, 2025). "Carriers of TREM2 mutations exhibit increased amyloid deposition and accelerated cognitive decline, perhaps due to a dysregulated microglial response to Aβ." (PMID 40507855, 2025). "Studies in AD mouse models have linked TREM2 deficiency with impairments in synaptic structure and cognitive decline, indicating that proper synaptic pruning, which is essential for normal cognition, is compromised under TREM2 deficiency." (PMID 38912524, 2024). "The TREM2 R47H gene variant is associated with changes in cognitive decline in HD patients, and rs1927911 and rs10116253 TLR4 single nucleotide polymorphisms are associated with the rate of motor decline." (PMID 38459557, 2024). "Many genetic variants associated with cognitive decline and AD are expressed in microglia, such as triggering receptor expressed on myeloid cells-2 (TREM2)." (PMID 38076538, 2023). "The genetic variants of molecules associated with ‘‘microgliopathies’’, including the triggering receptor expressed in myeloid cells-2 (TREM2), result in increased risk of developing AD and cognitive decline." (PMID 37513845, 2023). "Our results showed that increased levels of TREM2 were associated with slower amyloid accumulation in A+ individuals in addition to slower tau deposition and cognitive decline in A+T+ subjects." (PMID 37118533, 2022). "The cerebrospinal fluid (CSF) levels of soluble TREM2 (sTREM2) have emerged as a valuable biomarker for the disease progression in AD and higher CSF levels of sTREM2 are linked to slower cognitive decline." (PMID 34893068, 2021). "The KO caused a significant increase in IL-34, TREM2, and β-Catenin gene expression together with the improvement of cognitive decline and a decrease in Aβ burden." (PMID 33402196, 2021). "We found that TREM2 rs1927911 was associated with the rate of cognitive decline, whereas TLR4 rs1927911 and TLR4 rs1927914 were both associated with the rate of motor decline." (PMID 31724242, 2020). "Protein quantitative trait analysis of human monocytes revealed that the rs6910730G variant in the TREM1 locus was associated with a decreased TREM1/TREM2 ratio and increased pathological features of AD and aging-related cognitive decline." (PMID 31426806, 2019). "TREM2 mutations clearly lead to cognitive decline in AD patients." (PMID 41280332, 2025). "Inhibiting the loss of TREM2 may be one of the mechanisms by which running exercise improved glucose metabolism in the hippocampus and rescued cognitive decline in APP/PS1 mice." (PMID 35123512, 2022). "Recently, it has been suggested that higher CSF sTREM2 attenuates risk for cognitive decline and TREM2 may be protective against the development of AD." (PMID 33981209, 2021). "Microglial activation augments AD pathogenesis, and thus, an altered expression of triggering receptor expressed on myeloid cells 2 (Trem2), that acts as a risk factor for AD, may reduce the compaction of Aβ and attenuate the cognitive decline." (PMID 35185512, 2021). "We also found that the TREM2 R47H gene variant was associated with changes in cognitive decline in the large cohort of HD patients, whereas 2 of 3 TLR4 single nucleotide polymorphisms assessed were associated with changes in motor progression in this same group." (PMID 31724242, 2020). "For example, TREM2 overexpression ameliorated synaptic protein dysregulation in models of anesthesia‐ and surgery‐induced cognitive decline in aging mice." (PMID 41476737, 2025).
cognitive decline (continued). "For instance, late-stage AD is characterized by increased expression of TREM2 and CD33, two genes involved in microglial activation and inflammation, correlating with rapid cognitive decline and neuronal loss." (PMID 40004464, 2025). "Despite conflicting pre-clinical findings on a protective vs. detrimental role of TREM2, our current and previous findings in humans favor a protective role of TREM2 against the development of AD pathology, AD-related cognitive decline and neurodegeneration." (PMID 33032659, 2020). "Upregulation of TREM2 mitigates cognitive decline by suppressing inflammatory response via PI3K/AKT pathway in epilepsy." (PMID 33065553, 2020). "TREM2 mutations have been associated with several neurodegenerative diseases and TREM1 variants with cognitive decline and Alzheimer-related amyloid pathology." (PMID 28303091, 2017). "TREM2 knockout exacerbated cognitive decline and Aβ pathology." (PMID 41484634, 2026). "The specific mutation, His157Tyr in TREM2, in particular, has been verified in connection with the clinical phenotype of FTD, as carrier patients presented with symptoms of behavioral changes and cognitive decline." (PMID 40806186, 2025). "Furthermore, the triggering receptor expressed on myeloid cell 2 (TREM2), which is involved in microglial activation, has been found to be reduced in aged AD rat models and to correlate with cognitive decline." (PMID 40565005, 2025). "Rare TREM2 variants are strongly associated with increased risk for AD, and individuals who carry these mutations show an earlier age of onset or more severe cognitive decline than noncarriers." (PMID 41280332, 2025). "In the brains of AD patients, TREM2 interacts with components of senile plaques, including Aβ, lipo-, and apolipoproteins; and the elevation of soluble TREM2 in cerebrospinal fluid (CSF) negatively correlated with plaque growth, cortical shrinkage, and cognitive decline." (PMID 36613460, 2022). "Indeed, TREM2/β-Catenin and IL-34 expression increase leading to a reduction of plaque volume and a delayed cognitive decline." (PMID 33402196, 2021). "Studies show that in early AD pathology, TREM2 is needed for clearance of early Aβ plaques and slowing of cognitive decline, while expression of TREM2 later in disease progression could lead to detrimental long-term consequences." (PMID 32425941, 2020). "In our previous study, we found that serum levels of soluble TREM2 are lower in VD patients than in healthy controls and TREM2 may be a potential predictive biomarker of cognitive decline in VD." (PMID 32617097, 2020). "Since the use of γ-secretase inhibitors to inhibit Aβ generation has largely failed clinically, alternative strategies such as targeting PS1/TREM2 trafficking may be more effective in reversing cognitive decline near the onset of AD." (PMID 29611543, 2017). "We hypothesized that disrupted TREM2 signaling serves as a critical mechanism linking chronic hyperglycemia to microglial dysfunction and aberrant Aβ accumulation in T1D, thereby contributing to cognitive decline." (PMID 41484634, 2026). "Upon inhibition of Aβ plaque clearance from ineffective TREM2 activity, subsequent amyloid accumulations in the brain would lead to sustained neuroinflammatory responses and neuronal death, thereby contributing to memory and cognitive decline, leading to AD onset." (PMID 40806186, 2025). "The TREM2-BAC x 5XFAD mice produced less cortical amyloid plaques than 5XFAD mice at 7 months and had similar performance in contextual fear conditioning tests compared to wildtype mice, indicating that TREM2 expression may somehow reduce the Aβ pathology and alleviate cognitive decline in AD." (PMID 33014535, 2020). "Beyond TREM2, CSF concentrations of chemokine motif ligand 2 (CCL2), mediating the chemotaxis of monocytes, are also predictive of cognitive decline in AD." (PMID 39472664, 2025).
cognitive decline (continued). "We found that cortical TREM2 levels were positively related to AD diagnosis, cognitive decline, and amyloid-β neuropathology but were not related to the proportion of activated microglia." (PMID 36966244, 2023). "Moreover, some non-drug treatments, for example, low-dose ionizing radiation (LDIR), may also affect the phenotype of microglia, increase TREM2 and CD206 expression in LPS-induced BV2 microglial cells, and attenuate Aβ deposition and cognitive decline ultimately." (PMID 35558075, 2022). "Based on a recent study, high levels of soluble TREM2 (sTREM2) helped to ameliorate the effects of APOE 4-carriage on the hippocampus atrophy and cognitive decline independent of AD pathology markers in cerebrospinal fluid." (PMID 35558075, 2022).
Stroke (52 papers, 2013 to 2026). Sudden impairment of blood flow to a part of the brain due to occlusion or rupture of an artery to the brain. "Mechanistically, excessive salt downregulates TREM2 expression in macrophages associated with decreased efferocytic capacity, excessive neural inflammation, and exacerbated stroke outcomes." (PMID 33845849, 2021). "Opposing effects were obtained by TREM2 overexpression, while TREM2 deficiency attenuated the phagocytic activities of microglia and exacerbated the ischemic damage in experimental stroke." (PMID 29027964, 2017). "Taken together, our data clearly link TREM2 in the sub-acute phase after stroke to an inflammatory response associated with microglial activation, followed by attraction of CD3-positive T-cells at the lesion site." (PMID 23301011, 2013). "The precise mechanism underlying this attenuated post-stroke inflammatory response in TREM2-KO mice remains to be elucidated." (PMID 23301011, 2013). "Further evidence reveals that TREM2-mediated microglial activity participates in synaptic loss regulation during brain injury and disease, providing key insights into the molecular basis of post-stroke neurological deficits and recovery." (PMID 40722349, 2025). "TREM2 overexpression has been shown to have the opposite effect, while TREM2 deficiency attenuates microglial phagocytic activity and exacerbates ischemic damage in experimental stroke." (PMID 36212660, 2022). "Alternatively, post-ischemic HSP60 induction may underlie the dramatic increase of TREM2 following stroke observed here." (PMID 23301011, 2013). "Whereas CCR1, CCR2 and CCR5 expression was found to be unchanged, a reduced gene transcription of the microglial-associated chemokine receptor CX3CR1 was observed after stroke in TREM2-KO mice compared to littermate control mice (12 h: to 79% ±6.7; 7 d: to 50% ±4.6, p≤0.05, n = 5/6 each)." (PMID 23301011, 2013). "In addition, TREM2 deficiency attenuates phagocytic activities of microglia in experimental stroke." (PMID 28592261, 2017). "The expression of pro-inflammatory cytokines (TNF-α, IL-1α, IL-1β) and chemokines (CCL2, CCL3), as well as the chemokine receptor CX3CR1, is reduced at 7 days after stroke in TREM2-KO mice, along with attenuated activation of microglia." (PMID 40242752, 2025). "Stroke model studies demonstrate that TREM2 functional defects directly inactivate microglial phagocytic capacity." (PMID 40722349, 2025). "As previously stated, the CX3CR1 and TREM2 pathways exhibit precise synergistic regulation that jointly controls acute neuroinflammatory dynamics after stroke." (PMID 40722349, 2025). "In another study, the role of TREM-2 in microglial phagocytosis was examined in a mouse model of stroke, highlighting worsened post-stroke neurological outcomes due to microglial hyperactivation." (PMID 39062850, 2024). "Our research corroborates these effects, as mice in EE demonstrated superior behavioral performance post-stroke and post-surgical stimulation compared to those in SE, with concurrent elevated TREM2 expression in their hippocampal tissue." (PMID 39758888, 2024). "In stroke and in the LPS-induced encephalopathy, overexpression of TREM2 promoted M2-polarization in LPS-treated microglia, which alleviated neuroinflammation and reduced the number of apoptotic neuron." (PMID 38236825, 2024). "The present study reveals a novel regenerative role of PE in white matter damage after stroke, which is mediated by upregulation of TREM2 and microglia-derived factor for oligodendrocytes regeneration." (PMID 36829205, 2023). "The findings showed that PE modulated microglial functional state and promoted remyelination after stroke by up-regulating TREM2." (PMID 36829205, 2023). "The present study reveals a novel regenerative role of PE in white matter injury after stroke, which is mediated by upregulation of TREM2 and microglia-derived factor for oligodendrocytes regeneration." (PMID 36829205, 2023).
Stroke (continued). "We first noted greater total densities of CD68+ and TREM2+ cells per mm2 in the frontal WM compared to the overlying cortex across the stroke cases and controls (p = 0.001)." (PMID 35748290, 2022). "In the stroke research field, TREM2 has been demonstrated to have neuroprotective effects in intracerebral haemorrhage, ischaemic stroke, and subarachnoid haemorrhage." (PMID 36463233, 2022). "It was also reported that TREM2 enhanced the phagocytic activity of microglia and significantly attenuated ischaemic injury in experimental stroke." (PMID 35869493, 2022). "Triggering receptor expressed on myeloid cells 2 (TREM2) has been proven to exert neuroprotective effects in neurodegenerative diseases and stroke by modulating neuroinflammation, and promoting phagocytosis and cell survival." (PMID 36463233, 2022). "We then tested the TREM2 level in monocytes of AIS patients and evaluated the relationship between TREM2 expression and stroke outcomes." (PMID 33845849, 2021). "Knockout of the microglial phagocytic receptor TREM2 increased infarct size and functional deficits after stroke in mice, potentially by reducing phagocytosis." (PMID 34948237, 2021). "TREM2 expression in monocytes was downregulated in stroke patients with high urine sodium concentration compared with those with normal diets using FACS." (PMID 33845849, 2021). "With the application of bone marrow chimeric mice, this team further addressed that intact microglia TREM2 is more important for beneficial phagocytosis and stroke recovery than that of circulating macrophage." (PMID 35082781, 2021). "In line with a progressive elevation of the anti-inflammatory/neuroprotective response of microglia and infiltrating macrophages in the post stroke period, at 7 days Mrc1, Tgfb1 and Trem2 transcripts also significantly increased." (PMID 33246465, 2020). "In fact, mice deficient in triggering receptor expressed on myeloid cells 2 (TREM2) show impaired phagocytosis, increased infarct size, and worse functional outcome after stroke." (PMID 33058417, 2020). "The microglia cell surface receptor (triggering receptor expressed on myeloid cells‐2; TREM2) regulates the production of pro‐ and antiinflammatory mediators after stroke." (PMID 32757264, 2020). "Depletion of microglial TREM2 correlates with exacerbated outcomes from experimental stroke and impeded phagocytosis, whereas receptor expression led to reduced infarct volumes and neurological recovery." (PMID 32757264, 2020). "In vivo, TREM2 silencing exacerbated stroke outcome as demonstrated by an increased lesion volume, the number of apoptotic neurons and a decrease in neurological function measured with the Modified Garcia Score." (PMID 31379859, 2019). "The first and potentially the most thorough investigated role of TREM2 in stroke is its function in phagocytosis." (PMID 31379859, 2019). "Our previous study found that activation or upregulation of triggering receptor expressed on myeloid cells 2 (TREM2) promoted the phenotypic conversion of microglia and thus decreased the number of apoptotic neurons in stroke mice." (PMID 31866829, 2019). "This review aims to provide an overview on the regulation and potential role of TREM2 in stroke pathobiology and resolution with a focus on microglial function as its role in these processes remains to be elucidated." (PMID 31379859, 2019). "Confocal microscopy confirmed these results as a significantly reduced direct contact between activated macrophages and TUNEL-positive dying cells at the stroke site in TREM2 KO mice was observed (<4% compared to almost 40% in WT animals)." (PMID 31379859, 2019). "TREM2 was shown to be activated by nucleotides and lipid mediators, key factors that are secreted in the extracellular stroke environment by apoptotic neurons and cell/myelin debris." (PMID 31379859, 2019).